NT5C (5', 3'-nucleotidase, cytosolic)
Description:
Dephosphorylates the 5' and 2'(3')-phosphates of deoxyribonucleotides, with a preference for dUMP (Ref.12). Also dephosphsphorylates dTMP, exhibits intermediate activity towards dGMP, and low activity towards dCMP and dAMP (By similarity).
Synonyms: dNT-1; DNT1; UMPH2; PN-I; cdN; DNT; HEL74; P5N2; PN-II
Tractability: Small molecule: a structure with a bound ligand is known. PROTAC: ubiquitination databases record sites on it; its protein half-life has been measured.
Target class: Enzyme; Phosphatase
Gene: Protein-coding gene on chromosome 17 (75,130,225 to 75,131,776, reverse strand). Ensembl gene ENSG00000125458.
Subcellular location: Cytoplasm
Subcellular location (Human Protein Atlas): Cytosol
Pathways (Reactome):
Metabolism: Purine catabolism; Pyrimidine catabolism
Gene Ontology:
Molecular function: identical protein binding; nucleotidase activity; pyrimidine nucleotide binding; 3'-nucleotidase activity; 5'-nucleotidase activity; 5'-deoxynucleotidase activity; phosphatase activity
Biological process: dephosphorylation; pyrimidine deoxyribonucleotide catabolic process; dAMP catabolic process; dCMP catabolic process; dTMP catabolic process; GMP catabolic process; IMP catabolic process; TMP catabolic process; UMP catabolic process; deoxyribonucleotide catabolic process; dGMP catabolic process; dUMP catabolic process
Cellular component: cytoplasm; cytosol; extracellular exosome; mitochondrion; nucleus
Genetic constraint (gnomAD): Loss-of-function variants: 12 observed, 16.38 expected, observed/expected ratio (o/e) 0.73, 90% interval 0.47 to 1.19. The synonymous counts are far from expectation, so gnomAD's model fits this gene poorly and the ratio says little. Missense variants: 253 observed, 185.83 expected, observed/expected ratio (o/e) 1.36, 90% interval 1.23 to 1.51. Synonymous variants: 120 observed, 76.09 expected, observed/expected ratio (o/e) 1.58, 90% interval 1.36 to 1.83.
Homologues: Orthologues: macaque NT5C (96% identical), dog NT5C (88% identical), guinea pig NT5C (87% identical), pig NT5C (85% identical), mouse Nt5c (83% identical), rat Nt5c (82% identical), chimpanzee NT5C (72% identical), rabbit NT5C (64% identical). Paralogues in human: NT5M (59% identical).
Diseases named in the same sentence as NT5C in open-access papers:
NT5C is named in the same sentence as 10 diseases in open-access papers, as found by Europe PMC text mining. Sharing a sentence is not in itself a finding about the gene and the disease. The quoted sentences say what the papers report.
fibrosarcoma (1 paper, 2017). A malignant mesenchymal fibroblastic neoplasm affecting the soft tissue and bone. "We next examined the localization of NT5C in primary MEFs and in human HT1080 fibrosarcoma cells." (PMID 28059163, 2017).
leukemia (1 paper, 2025). A malignant (clonal) hematologic disorder, involving hematopoietic stem cells and characterized by the presence of primitive or atypical myeloid or lymphoid cells in the bone marrow and the blood. "Notably, abnormal expression of NT5C, which is related to pyrimidine metabolism, has been associated with resistance to chemotherapies (e.g., cytarabine) in pediatric leukemia." (PMID 41226303, 2025).
cancer (4 papers, 2021 to 2025). A tumor composed of atypical neoplastic, often pleomorphic cells that invade other tissues. "DUT and NT5C are enzymes involved in nucleotide metabolism and are associated with the prognosis of cancer patients." (PMID 34885971, 2021). "Finally, four novel enzymes with unappreciated biological functions in cancer were identified, namely thromboxane A synthase 1 (TBXAS1), 5′,3′‐nucleotidase, cytosolic (NT5C), glycosyltransferase 8 domain containing 2 (GLT8D2) and reticulon 4 interacting protein 1 (RTN4IP1)." (PMID 39757767, 2025).
NT5C also shares sentences with these, for which no sentence is quoted: tumor (2 papers); attention deficit-hyperactivity disorder (1); cardiac diseases (1); meningioma (1); obsessive-compulsive disorder (1); psychiatric disorder (1); schizophrenia (1).